MYOZ3 (myozenin 3)
Description:
Myozenins may serve as intracellular binding proteins involved in linking Z line proteins such as alpha-actinin, gamma-filamin, TCAP/telethonin, LDB3/ZASP and localizing calcineurin signaling to the sarcomere. Plays an important role in the modulation of calcineurin signaling. May play a role in myofibrillogenesis.
Synonyms: FRP3; CS-3; CS3; FATZ-3
Tractability: No criterion of Open Targets' tractability assessment is met for any kind of drug.
Gene: Protein-coding gene on chromosome 5 (150,660,450 to 150,680,022, forward strand). Ensembl gene ENSG00000164591.
Subcellular location: Cytoplasm, myofibril, sarcomere, Z line
Gene Ontology:
Molecular function: protein binding; actin binding; FATZ binding; telethonin binding
Cellular component: actin cytoskeleton; Z disc
Genetic constraint (gnomAD): Loss-of-function variants: 19 observed, 26.69 expected, observed/expected ratio (o/e) 0.71, 90% interval 0.5 to 1.04. The upper end of that interval is the gene's LOEUF score, 1.04, which puts it in group 4 of 6, group 1 being the genes least tolerant of losing a copy. Missense variants: 322 observed, 339.37 expected, observed/expected ratio (o/e) 0.95, 90% interval 0.87 to 1.04. Synonymous variants: 135 observed, 142.73 expected, observed/expected ratio (o/e) 0.95, 90% interval 0.82 to 1.09.
Homologues: Orthologues: chimpanzee MYOZ3 (99% identical), macaque MYOZ3 (97% identical), dog MYOZ3 (82% identical), rabbit MYOZ3 (78% identical), rat Myoz3 (75% identical), mouse Myoz3 (74% identical), guinea pig MYOZ3 (73% identical), pig MYOZ3 (64% identical), tropical clawed frog myoz3 (35% identical), zebrafish myoz3a (32% identical). Paralogues in human: MYOZ2 (34% identical), MYOZ1 (27% identical).
Diseases named in the same sentence as MYOZ3 in open-access papers:
MYOZ3 is named in the same sentence as 8 diseases in open-access papers, as found by Europe PMC text mining. Sharing a sentence is not in itself a finding about the gene and the disease. The quoted sentences say what the papers report.
bacteremia (1 paper, 2025). "Children with unexplained fever and high CRP had a gene expression profile distinct from those with bacteremia, including downregulated CXCL1, MYOZ3, and HSPG2." (PMID 40806258, 2025).
cerebrovascular diseases (1 paper, 2024). "There were 6 genes related to cardiovascular and cerebrovascular diseases, which were Fgd3, Myoz3, AC095693.1, Adamts3, PDGFA and PDGFRα." (PMID 38195688, 2024).
hypertrophic cardiomyopathy (1 paper, 2013). A condition in which the myocardium is hypertrophied without an obvious cause. "In cardiac and skeletal muscle, the products of MYOZ2 and MYOZ3 genes appear to influence the expression of calcineurin, which plays an important role in hypertrophic cardiomyopathy and skeletal muscle fiber differentiation." (PMID 24367523, 2013).
Sepsis (1 paper, 2025). Sepsis is defined as life-threatening organ dysfunction caused by a dysregulated host response to infection. "Genes and pathways related to cardiac and vascular function were upregulated, such as MYOZ3 and HSPG2, which may reflect hyperdynamic cardiac function and vascular dysregulation during sepsis." (PMID 40806258, 2025).
cancer (3 papers, 2014 to 2025). A tumor composed of atypical neoplastic, often pleomorphic cells that invade other tissues. "Further validation in four independent cohorts showed that KEAP1, SRI, MFAP1, MFAP2, INCENP, and KIF21B were consistently upregulated in cancer tissues, while MYOZ3, DST, and TIAM1 were consistently downregulated." (PMID 40228435, 2025). "Heatmap results showed that NRP1, MFAP2, KLC1, DST, and MYOZ3 were generally downregulated in cancer cell lines, while KIF21B, SRI, INCENP, and KEAP1 were also downregulated." (PMID 40228435, 2025). "Similar to our findings using microarray analysis, FoxO was necessary for the cancer-induced upregulation of Cebpb, Fos, Fbxo31 and Psma2, and was necessary for the cancer-induced downregulation of Col6a2, Myoz3 and Tnc (interaction effect, p < 0.05, AAV9-ev C26 vs. AAV9-d.n.FoxO C26, p < 0.05)." (PMID 25539728, 2014).
tumor (1 paper, 2025). "MYOZ3 is involved in muscle development and cell motility, and its function in tumor cells may relate to cellular migration and invasiveness." (PMID 40228435, 2025).
MYOZ3 also shares sentences with these, for which no sentence is quoted: mastitis (1 paper); muscular dystrophy (1).